CAPN13 (calpain 13)
Description:
Probable non-lysosomal thiol-protease.
Synonyms: FLJ23523
Tractability: PROTAC: ubiquitination databases record sites on it.
Gene: Protein-coding gene on chromosome 2 (30,722,771 to 30,820,542, reverse strand). Ensembl gene ENSG00000162949.
Subcellular location (Human Protein Atlas): Nucleoplasm
Pathways (Reactome):
Extracellular matrix organization: Degradation of the extracellular matrix
Gene Ontology:
Molecular function: calcium-dependent cysteine-type endopeptidase activity
Biological process: proteolysis
Cellular component: cytoplasm
Genetic constraint (gnomAD): Loss-of-function variants: 81 observed, 86.93 expected, observed/expected ratio (o/e) 0.93, 90% interval 0.78 to 1.12. The upper end of that interval is the gene's LOEUF score, 1.12, which puts it in group 4 of 6, group 1 being the genes least tolerant of losing a copy. Missense variants: 857 observed, 828.04 expected, observed/expected ratio (o/e) 1.03, 90% interval 0.98 to 1.1. Synonymous variants: 322 observed, 300.52 expected, observed/expected ratio (o/e) 1.07, 90% interval 0.98 to 1.17.
Homologues: Orthologues: chimpanzee CAPN13 (99% identical), macaque CAPN13 (93% identical), rabbit CAPN13 (70% identical), guinea pig CAPN13 (68% identical), mouse Capn13 (67% identical), rat Capn13 (67% identical), dog CAPN13 (64% identical), pig CAPN13 (63% identical), tropical clawed frog capn13 (39% identical), tropical clawed frog capn10l (35% identical), Drosophila melanogaster CalpB (30% identical), Caenorhabditis elegans clp-1 (26% identical), and 8 more. Paralogues in human: CAPN14 (35% identical), CAPN11 (34% identical), CAPN1 (34% identical), CAPN8 (33% identical), CAPN3 (32% identical), CAPN2 (31% identical), CAPN12 (30% identical), CAPN9 (30% identical), CAPN5 (24% identical), CAPN6 (22% identical), CAPN10 (22% identical), CAPN7 (21% identical), and 8 more.
Diseases named in the same sentence as CAPN13 in open-access papers:
CAPN13 is named in the same sentence as 8 diseases in open-access papers, as found by Europe PMC text mining. Sharing a sentence is not in itself a finding about the gene and the disease. The quoted sentences say what the papers report.
breast carcinoma (2 papers, 2013 to 2020). "An association between increased GReX and increased risk of breast cancer-specific mortality was identified for CAPN13 (2p23.1)." (PMID 32079541, 2020). "Less is known about the involvement of SERPINB5 and CAPN13 in breast cancer survival, though they have been identified in studies into breast cancer progression." (PMID 32079541, 2020). "In parallel studies for downregulated genes, we were able to identify seven genes with mutations in colon cancer (DPP10, PCSK2, ADAM33, RELN, CAPN13, ADAMTS1 and ADAMTS15), and five genes with mutations in breast carcinomas (MASP3, ABHD12B, TLL1, CPA3 and DPP6)." (PMID 24243807, 2013). "This conditional analysis suggests that the GReX of AURKA, CAPN13, and SERPINB5 may be associated with breast cancer-specific survival independent of the GWAS-identified variant." (PMID 32079541, 2020).
Hypertension (1 paper, 2020). The presence of chronic increased pressure in the systemic arterial system. "Promising candidate genes included CAPN13, a gene previously associated to hypertension in humans and LCLAT1, previously identified to control development of hematopoietic and endothelial lineages in mice embryos." (PMID 32719722, 2020).
Parkinson disease (1 paper, 2020). A progressive degenerative disorder of the central nervous system characterized by loss of dopamine producing neurons in the substantia nigra and the presence of Lewy bodies in the substantia nigra and locus coeruleus. "The predisposition genes potentially linked to the neurological form of CD were identified by messenger-RNA (mRNA) profiling: CADPS2 (ASD), CAPN13 (AD), BACE2 (AD, DS), DSCR5 (DS), and PINK1 (Parkinson’s Disease (PD)." (PMID 32751379, 2020).
cardiovascular disease (1 paper, 2016). "The eight significant SNPs identified in Model 1 are located in five genes —LRP8, CAPN13, MITF, SGCD and MLL3—previously implicated in BP variation or cardiovascular disease." (PMID 28002425, 2016).
CAPN13 also shares sentences with these, for which no sentence is quoted: tumor (3 papers); chronic sinusitis (1); colon cancer (1); type 2 diabetic (1).